ULK1 (unc-51 like autophagy activating kinase 1)
Diseases named in the same sentence as ULK1 in open-access papers (continued):
Sharing a sentence is not in itself a finding about the gene and the disease.
nonalcoholic steatohepatitis (2 papers, 2021 to 2023). "AA-24-a was shown to ameliorate nonalcoholic steatohepatitis by inhibiting oxidative stress and stimulating autophagy in both mouse model and human hepatic stellate cells, and to stimulate autophagy via the AMPK/mTOR/ULK1 pathway." (PMID 33888116, 2021).
protein folding disorders (2 papers, 2015 to 2020). "Our results thus provide a rationale for the development of therapeutics against human diseases associated with protein aggregates(proteinopathies), based on ULK1 and p62 interaction and signaling." (PMID 25723488, 2015).
psoriasis (2 papers, 2021 to 2024). An autoimmune condition characterized by red, well-delineated plaques with silvery scales that are usually on the extensor surfaces and scalp. "Herein, we showed that ULK1, the key autophagic initiator, and its phosphorylation at Ser556 were distinctively decreased in the epidermis from lesional skin of psoriasis patients." (PMID 34421918, 2021). "Together, these findings suggested that the downregulation of phosphorylated ULK1 limited psoriasis-like skin inflammation induced by IMQ." (PMID 34421918, 2021). "Herein, we reported that both ULK1 and its functional form of phosphorylated ULK1 (pULK1) was downregulated in the lesional epidermis from psoriasis patients." (PMID 34421918, 2021). "To this end, we first tested the expression levels of ULK1 on neutrophils between healthy donors and psoriasis patients." (PMID 34421918, 2021). "Topical application of SBI0206965, a selective ULK1 inhibitor, significantly attenuated epidermal hyperplasia, infiltration of neutrophils, and transcripts of the psoriasis-related markers in imiquimod (IMQ)-induced psoriasiform dermatitis (PsD)." (PMID 34421918, 2021). "Contrary to what we observed in the epidermis, the mRNA levels of ULK1 on neutrophil was comparable between healthy donors and psoriasis." (PMID 34421918, 2021). "Taken together, our findings suggest a possible self-regulatory process by downregulating ULK1 to maintain skin homeostasis in psoriasis via interfering with keratinocyte-neutrophil interplay." (PMID 34421918, 2021). "Further studies are required to elucidate the mechanisms of ULK1 regulating cytokine production under the settings of psoriasis." (PMID 34421918, 2021). "We then adopted the IMQ-induced psoriasis model to investigate whether dysregulation of ULK1 was involved in the pathogenesis of psoriasis." (PMID 34421918, 2021). "To investigate whether the reduction of ULK1 expression in keratinocytes participates in psoriasis development, we further transfected HaCat cells with small interfering RNA against ULK1 (ULK1-siRNA) or non-targeting negative control siRNA (NC-siRNA)." (PMID 34421918, 2021). "Even much less is known about the role of ULK1 in inflammatory skin disease like psoriasis." (PMID 34421918, 2021). "ULK1 might be a potential target for preventing or treating psoriasis." (PMID 34421918, 2021). "Inhibitors of ULK1 may provide a novel therapeutic option for the treatment of psoriasis." (PMID 34421918, 2021). "However, psoriatic KCs already exhibited a lower level of ULK1 as well as phosphorylation at Ser556, implicating that a self-regulatory process exists to downregulate ULK1 in maintaining epidermal homeostasis in the context of psoriasis." (PMID 34421918, 2021). "ULK1 inhibitor might be a potential option for treating or preventing relapse of psoriasis." (PMID 34421918, 2021). "In line with our results, IMQ was shown to reduce levels of autophagy-related proteins, including phosphorylated ULK-1, ATG-7, and LC3A/B, in murine models of psoriasis-like inflammation." (PMID 39337618, 2024). "We were also unable to detect phosphorylation of ULK1 on neutrophils from either healthy subjects or psoriasis patients using western blot (data not shown)." (PMID 34421918, 2021). "Albeit not statistically significant, IHC analysis further suggested a trend towards lower levels of total ULK1 and phosphorylation of ULK1 in the non-lesional epidermis from psoriasis patients versus normal epidermis from healthy donors." (PMID 34421918, 2021). "Downregulation of ULK1 with siRNA did not affect the expression of most psoriasis-related cytokines in PHK without stimulation but increased the transcripts of TNF and CXCL8 in the presence of IL-17A." (PMID 34421918, 2021). "However, we observed a positive correlation of ULK1 with myeloperoxidase (MPO), a major protein constituent of granules, in neutrophils from both healthy donors and patients with psoriasis." (PMID 34421918, 2021).
psoriasis (continued). "An additional correlation of ULK1 with other granule-derived antimicrobial peptides and enzymes, including Cathelicidin (LL37) and elastase (ELANE), was found exclusively in psoriasis patients but not health donors." (PMID 34421918, 2021).
renal cell carcinoma (2 papers, 2020 to 2023). "An increased expression of TRPM3 in renal cell carcinoma leads to Ca2+ influx, which elicits the activation of CaMKII, 5′-AMP-activated protein kinase (AMPK), and Unc-51-like autophagy-activating kinase 1 (ULK1), as well as the formation of phagophore." (PMID 37892239, 2023).
sarcoma (2 papers, 2019 to 2021). A usually aggressive malignant neoplasm of the soft tissue or bone. "Exposure of sarcoma cells to [pazopanib + entinostat] caused activation of ATM, AMPK, and ULK-1 S317 phosphorylation." (PMID 31380285, 2019).
spinal cord injury (2 papers, 2020 to 2021). Penetrating and non-penetrating injuries to the spinal cord resulting from traumatic external forces (e.g., WOUNDS, GUNSHOT; WHIPLASH INJURIES; etc.). "In addition, AAV.ULK1.DN increases neuronal survival and enhances axonal regeneration after optic nerve lesion, and promotes long-term axonal protection after spinal cord injury (SCI) in vivo." (PMID 33637688, 2021). "Recently, we demonstrated increased levels of autophagic proteins, including Unc-51 like autophagy activating kinase 1 (ULK1), early in degenerating axons after spinal cord injury (SCI)." (PMID 32341448, 2020).
type 1 diabetes (2 papers, 2019 to 2021). "Specifically, niclosamide ethanolamine salt could reduce the over expression of autophagy-related proteins, including p-AMPK (Thr172), FoxO3a, p-ULK1 (Ser555), LC3B II, and p-p38 in gastrocnemius muscle of the type 1 diabetes mice." (PMID 34107998, 2021).
ZIKV infection (2 papers, 2022 to 2024). "AMPK and its downstream ULK1-Ser556 signaling pathway are centrally involved in the regulation of the LD metabolism required for ZIKV infection." (PMID 36405969, 2022). "The effects of AMPK silencing on ZIKV infection and the ULK1 and mTOR signaling pathways, two pathways downstream of AMPK, were evaluated via western blotting." (PMID 36405969, 2022). "The activities of mammalian target of rapamycin (mTOR) at Ser-2448 and ULK1 at Ser-757 were suppressed independently of AMPK during ZIKV infection." (PMID 36405969, 2022). "Moreover, ZIKV infection increased Ser556 phosphorylation of ULK1 and significantly reduced Ser2448 phosphorylation of mTOR and Ser757 phosphorylation of ULK1." (PMID 36405969, 2022). "Likewise, the ratio of Ser556–phosphorylated ULK1 to total ULK1 was also increased after ZIKV infection, whereas the ratios of Ser2448–phosphorylated mTOR to total mTOR and Ser757–phosphorylated ULK1 to total ULK1 were decreased." (PMID 36405969, 2022). "Autophagy flux was found to be activated by ZIKV infection, triggering the AMPK-mediated activation of Unc-51-like kinase 1 (ULK-1), initiating autophagy in the ER and potentially lipophagy in LDs." (PMID 38674592, 2024). "In this study, increased phosphorylation of ULK1-Ser556 and reduced phosphorylation of mTOR-Ser2448 and ULK1-Ser757 were observed along with increased AMPK activity after ZIKV infection." (PMID 36405969, 2022).
acute promyelocytic leukemia (1 paper, 2020). An aggressive form of acute myeloid leukemia (AML), characterized by arrest of leukocyte differentiation at the promyelocyte stage, due to a specific chromosomal translocation t(15;17) in myeloid cells. "A recent study has shown that HOTAIRM1 can enhance autophagosome formation to degrade oncoprotein PML–RARA by sponging miR-20a to upregulate ULK1 in acute promyelocytic leukemia (APL)-ascites mouse model and APL cell lines." (PMID 33050642, 2020).
adenomyosis (1 paper, 2024). The growth of endometrial tissue inside the muscular wall of the uterine corpus. "Research supports that the downregulation of the tumor suppressor gene GRIM-19 in adenomyosis increases autophagy levels via the AMPK/ULK1 signaling pathway, allowing adenomyosis nidus to generate the energy and nutrients necessary for its survival and growth." (PMID 39768424, 2024).
Angelman syndrome (1 paper, 2024). A neurogenetic disorder characterized by severe intellectual deficit and distinct facial dysmorphic features. "Taking into account all the evidence presented in this study, it suggests that targeting USP20 and/or ULK1 could potentially hold therapeutic promise for individuals affected by HERC2-related disorder and Angelman syndrome." (PMID 38570483, 2024).
autosomal dominant retinitis pigmentosa (1 paper, 2025). Autosomal dominant retinitis pigmentosa (RP) is an autosomally dominant inherited retinal dystrophy leading to progressive loss of the photoreceptors and retinal pigment epithelium and resulting in blindness usually after several decades. "The aberrant AS of ULK1 (unc-51 like autophagy activating kinase 1), a key initiation factor capable of being phosphorylated by mTOR and AMPK at distinct residues for autophagy induction, has been linked to autosomal dominant retinitis pigmentosa caused by the deficiency of splicing factor PRPF8." (PMID 41271632, 2025).
B-cell lymphoma (1 paper, 2022). "Together, the increase of PI(18:1/18:1) in B-cell lymphoma is associated with elevated mTORC1 activity and inhibition of ULK1, indicative of impaired autophagy." (PMID 35624087, 2022).
benign ovarian tumors (1 paper, 2024). "Compared to normal ovarian tissue, protein levels of ULK1 were elevated in primary EOC and epithelial ovarian borderline tumor tissues, with no significant change observed in benign ovarian tumors." (PMID 38286802, 2024).
bone resorption disease (1 paper, 2021). A disease that has its basis in the disruption of bone resorption. "This study revealed the molecular mechanism by which ULK1 regulates OC differentiation and determined that ULK1 is an effective target for the treatment of abnormal bone resorption diseases." (PMID 34820053, 2021). "This demonstrates the feasibility of the use of ULK1 as a therapeutic target for excessive bone resorption diseases." (PMID 34820053, 2021).
brain tumor (1 paper, 2022). "Inhibition of ULK1 R170me2s abolished hypoxia-triggered autophagy and impaired brain tumor development." (PMID 35246531, 2022).
Chronic colitis (1 paper, 2024). A chronic inflammatory disease of the large intestine (colon, cecum and rectum). "In untreated rats with chronic colitis, there was a significant decrease in the levels of ULK1 and Beclin 1 compared with the control, healthy group." (PMID 39359253, 2024). "However, upon treatment with either 5 mg/kg or 10 mg/kg of BMS-477118, the levels of ULK1 and Beclin 1 in the chronic colitis group were significantly increased compared to the untreated chronic colitis group (respectively)." (PMID 39359253, 2024).
chronic kidney disease (1 paper, 2017). Impairment of the renal function secondary to chronic kidney damage persisting for three or more months. "ULK1 and ATG3 are autophagy associated genes wherein the components of the process are well deciphered in chronic kidney disease by affecting the mTOR pathway." (PMID 28349958, 2017).
cognitive decline (1 paper, 2025). "To investigate whether changes in mitophagy reflect cognitive decline in FTLD individuals, we correlated the levels of mitophagy biomarkers (PINK1, ULK1, BNIP3L, TFEB) with global cognition (MMSE) and cognitive composite scores." (PMID 39972393, 2025).
colorectal adenocarcinoma (1 paper, 2022). The most common type of colorectal carcinoma. "Recently, there is a study has shown that ULK1 is the most frequently mutated gene in The Cancer Genome Atlas (TCGA)-colorectal adenocarcinoma dataset, implying that ULK1 and its regulatory network may be closely related to colorectal carcinogenesis." (PMID 36172152, 2022).
colorectal tumor (1 paper, 2018). "In general, F. nucleatum promotes CRC chemoresistance by activating autophagosome formation and subsequently inducing autophagy-related proteins, such as pULK1, ULK1, and ATG7, in colorectal tumor cells." (PMID 30065719, 2018).
COVID-19 (1 paper, 2021). A disease caused by infection with severe acute respiratory syndrome coronavirus 2. "It was found that transcript levels of key factors promoting autophagy, i.e. ULK-1, ATG5, UVRAG, AMBRA, PIK3C3, and LC3, are significantly reduced in mononuclear cells of COVID-19 patients compared to healthy controls, and the phenomenon was more pronounced in severe COVID-19 patients." (PMID 33692788, 2021).
dengue virus infection (1 paper, 2020). "Other canonical autophagy factors, specifically ULK1, Beclin-1, and ATG5 are dispensable during dengue virus infection." (PMID 33173007, 2020).
dysplasia (1 paper, 2025). A usually neoplastic transformation of the cell, associated with altered architectural tissue patterns. "In summary, this section identifies SNHG1 as a clinically and mechanistically relevant lncRNA that modulates the interaction between ULK1 and Notch1, and is significantly upregulated in BE patients who later developed dysplasia." (PMID 40629071, 2025).
echovirus infection (1 paper, 2023). "Our findings suggest that autophagy can be induced by echovirus infection via regulating mTOR/ULK1 signaling pathway and exhibits a proviral function, revealing the potential role of autophagy in echovirus infection." (PMID 37114059, 2023). "Therefore, further studies may be needed to elucidate the mechanism by which echovirus infection regulates mTOR/ULK1 signaling pathway." (PMID 37114059, 2023). "Furthermore, phosphorylated mTOR and ULK1 were both decreased upon echovirus infection." (PMID 37114059, 2023).
ependymoma (1 paper, 2024). A WHO grade II, slow growing tumor of children and young adults, usually located intraventricularly. "Furthermore, TPR protects cells from RNA-mediated replication stress by regulating heat-shock transcription factor 1 (HSF1) mRNA trafficking, maintaining mTORC1 activity to phosphorylate Unc-51-like kinase 1 (ULK1), and preventing macroautophagy/autophagy induction in ependymoma." (PMID 39080077, 2024).
epithelial ovarian borderline tumor (1 paper, 2024). "We then investigated ULK1 expression in 78 primary EOC specimens, 14 epithelial ovarian borderline tumor specimens, 6 epithelial ovarian benign tumor specimens, and 5 normal ovarian specimens through IHC assays." (PMID 38286802, 2024).
epithelioid sarcoma (1 paper, 2021). An aggressive malignant neoplasm of uncertain differentiation, characterized by the presence of epithelioid cells forming nodular patterns. "Our results are in line with all this evidence and support the key role of CHIR99021 in mediating autophagy activation via AMPK/mTORC1/ULK1 in epithelioid sarcoma cells." (PMID 34681807, 2021).
experimental autoimmune encephalomyelitis (1 paper, 2023). An autoimmune demyelinating disease of the central nervous system that is produced experimentally in animals by the injection of homogenized brain or spinal cord in Freund's adjuvant. "Microglial deletion of ATG7 but not ULK1 (ortholog of Atg1) leads to defective myelin degradation and impaired recovery from experimental autoimmune encephalomyelitis." (PMID 37248218, 2023).
Fanconi anemia (1 paper, 2023). Fanconi anemia (FA) is a hereditary DNA repair disorder characterized by progressive pancytopenia with bone marrow failure, variable congenital malformations and predisposition to develop hematological or solid tumors. "To date, studies involving USP1 have been limited to the extent to which USP1 is important in promoting DNA damage repair in Fanconi anemia or regulating autophagy via ULK1 deubiqitination." (PMID 38012162, 2023).
frontotemporal dementia (1 paper, 2020). Frontotemporal dementia (FTD) comprises a group of neurodegenerative disorders, characterized by progressive changes in behavior, executive dysfunction and language impairment, as a result of degeneration of the medial prefrontal and frontoinsular cortices. "An initiation defect is also linked to ALS/frontotemporal Dementia due to inhibited trafficking of ULK1 to autophagy initiation sites." (PMID 32526847, 2020).
gastric tumor (1 paper, 2023). "Among autophagy genes in the Reactome database, PRMT1 was negatively correlated with genes such as ATG9A, DYNC1H1, EPAS1, PINK1, TSC1, TUBB6, and ULK1 in gastric tumor tissues (STAD-TCGA) and positively correlated with HMMR, ESCO2, CHAC2, and NUDT6 (STAD-TCGA)." (PMID 37564212, 2023).
HIV-1 infection (1 paper, 2020). The type species of lentivirus and the etiologic agent of acquired immunodeficiency syndrome (AIDS). "We next tested whether priming with HIV-1 CA P90A could attenuate WT HIV-1 infection in ULK1 and BECN1 knockout THP-1 cells." (PMID 33052966, 2020).
Hypertension (1 paper, 2018). The presence of chronic increased pressure in the systemic arterial system. "Additionally, our data demonstrated that a maternal high-fructose diet combined with a post-weaning high-fat diet, but not high-fat diet reduced Ulk1, Atg5, and Nrf2 mRNA levels, induced a greater degree of oxidative stress and hypertension." (PMID 29315230, 2018).
hypoxic-ischemic encephalopathy (1 paper, 2025). "In hypoxic-ischemic encephalopathy (HIE), treatment with CpG-ODN increases the phosphorylation of AMPK and its downstream targets (including ULK1, AMBRA1, LC3II/I, and LAMP1) and inhibition of TLR9 or AMPK reverses these effects, leading to decreased autophagy and poorer neurobehavioral outcomes." (PMID 40558558, 2025).
idiopathic membranous nephropathy (1 paper, 2021). "In idiopathic membranous nephropathy, sPLA2-IB and PLA2R cause podocyte injury by activating the p38MAPK/mTOR/ULK1 signaling pathway that is mediated by insufficient autophagy." (PMID 34721589, 2021).
injury (1 paper, 2025). Damage inflicted on the body as the direct or indirect result of an external force, with or without disruption of structural continuity. "Specifically, Rd regulates autophagy through the AMPK/mTOR/ULK1 signaling pathway, both in TAA-induced acute liver injury in vivo and LPS-induced HSC-T6 cells in vitro." (PMID 39875579, 2025).
invasive breast carcinoma (1 paper, 2020). A carcinoma that infiltrates the breast parenchyma. "The phosphorylation level of Exo70 on Ser89 was significantly decreased in human invasive breast cancer tissues as compared to the adjacent normal tissues, and was positively correlated with the expression level of ULK1." (PMID 31913283, 2020).
iron metabolism disorders (1 paper, 2025). "The activation of ULK1 can promote autophagy and mitochondrial clearance while the inhibition of ULK1 may lead to iron metabolism disorders and the accumulation of lipid peroxidation, thereby affecting ferroptosis." (PMID 41311024, 2025).
lupus nephritis (1 paper, 2022). Glomerulonephritis in the context of systemic lupus erythematosus. "ULK1 was significantly higher in patients with lupus nephritis type IV and V-IV than in normal controls (p < 0.05), and its involvement in autophagy-related pathways influences the pathological process of lupus nephritis." (PMID 36114579, 2022).
lymphopenia (1 paper, 2016). Reduction in the number of lymphocytes. "In vivo transferred T-cells up-regulate expression of Bcl-2, FoxO1, Eomes and Atg7, enhance the phosphorylation of pSTAT5 and ULK1 and activate the mitochondrial biogenesis via IL-15 signaling in lymphopenia." (PMID 27158441, 2016).